RN7SKP262 (RN7SK pseudogene 262)
Gene: Miscellaneous RNA gene on chromosome 12 (25,779,287 to 25,779,569, reverse strand). Ensembl gene ENSG00000222950.
Homologues: Orthologues: chimpanzee 7SK (99% identical). Paralogues in human: 7SK (74% identical), RN7SKP118 (73% identical), RN7SKP189 (73% identical), RN7SKP246 (73% identical), RN7SKP37 (73% identical), RN7SKP163 (72% identical), RN7SKP176 (72% identical), RN7SKP204 (72% identical), RN7SKP250 (72% identical), RN7SKP95 (72% identical), RN7SKP192 (72% identical), RN7SKP255 (72% identical), and 284 more.